OR10Z1 (olfactory receptor family 10 subfamily Z member 1)
Description:
Odorant receptor.
Synonyms: OR1-15
Tractability: Antibody: UniProt places it where antibodies can reach, with medium confidence; UniProt predicts a signal peptide or a membrane-spanning region; its Gene Ontology location is reachable by antibodies, with medium confidence.
Gene: Protein-coding gene on chromosome 1 (158,605,268 to 158,612,514, forward strand). Ensembl gene ENSG00000198967.
Subcellular location: Cell membrane
Pathways (Reactome):
Sensory Perception: Expression and translocation of olfactory receptors
Gene Ontology:
Molecular function: odorant binding; olfactory receptor activity; G protein-coupled receptor activity
Biological process: detection of chemical stimulus involved in sensory perception of smell; G protein-coupled receptor signaling pathway
Cellular component: membrane; plasma membrane
Genetic constraint (gnomAD): Loss-of-function variants: 1 observed, 1.16 expected, observed/expected ratio (o/e) 0.86, 90% interval 0.24 to 1.88. That is too few expected variants to judge how well the gene tolerates losing a copy. Missense variants: 468 observed, 392.85 expected, observed/expected ratio (o/e) 1.19, 90% interval 1.1 to 1.29. Synonymous variants: 187 observed, 159.68 expected, observed/expected ratio (o/e) 1.17, 90% interval 1.04 to 1.32.
Homologues: Orthologues: chimpanzee OR10Z1 (99% identical), macaque OR10Z1 (94% identical), dog OR10Z1 (89% identical), rabbit OR10Z1 (88% identical), mouse Or10z1 (88% identical), pig OR10Z1 (86% identical), rat Or10z1 (86% identical), guinea pig OR10Z1 (82% identical). Paralogues in human: OR10R2 (54% identical), OR10J1 (53% identical), OR10T2 (53% identical), OR10J5 (50% identical), OR10K1 (50% identical), OR10J3 (48% identical), OR10K2 (48% identical), OR1E1 (47% identical), OR1E2 (46% identical), OR1L3 (45% identical), OR6N1 (45% identical), OR7C1 (45% identical), and 116 more.